CXCR4 (C-X-C motif chemokine receptor 4)
Diseases named in the same sentence as CXCR4 in open-access papers (continued):
Sharing a sentence is not in itself a finding about the gene and the disease.
breast carcinoma (continued). "E-selectin allows the entry of breast cancer cells into the bone marrow, whereas the CXCL12/CXCR4 signaling anchors breast cancer cells in the microenvironment." (PMID 33096815, 2020). "AMD3100, a CXCR4 inhibitor, was then used to examine the role of CXCR4 in breast cancer cell migration and invasion." (PMID 32836215, 2020). "CXCR4 enhances metastatic growth of breast cancer cells to bone, liver, and lung, tissues in which its ligand SDF-1 is expressed in high amounts." (PMID 32355198, 2020). "Another study showed that a C-terminal binding protein (CtBP)-dependent transcriptional repressor TSHZ2 of GLI1 is downregulated in breast cancer cell lines leading to overexpression of GLI-target genes such as CXCR4." (PMID 33096815, 2020). "By targeting CXCR4, miR-381 plays an important role in breast cancer cell proliferation, EMT, and metastasis." (PMID 33324542, 2020). "CXCL12 (also known as stromal cell-derived factor 1 (SDF-1)) is expressed by a variety of cells of the bone microenvironment including osteoblasts and endothelial cells while cancer cells including breast cancer cells express CXCR4, the receptor for CXCL12." (PMID 32092997, 2020). "The role of the CXCL12/CXCR4 axis in determining metastatic sites was first proposed in breast cancer." (PMID 32079335, 2020). "In view of the new results and in combination with earlier published data, we propose a model that explains the divergent roles of LASP1 and CXCR4 in solid breast cancer and in CML cells." (PMID 32075106, 2020). "This leads to the activation of the CXCL12/CXCR4 pathway in breast cancer cells supporting tumor cells stemness and growth in a paracrine manner." (PMID 33096815, 2020). "Dimerization seems to be another effective strategy to block the CXCL12/CXCR4 dependent migration in breast cancer." (PMID 33096815, 2020). "The CXCL12/CXCR4 signaling is involved in extraversion of metastatic breast cancer cells in the liver." (PMID 33096815, 2020). "Thymoquinone downregulated the expressions of CXCR4 in breast cancer cells in a time- and dose-dependent manner, demonstrating its anti-metastatic effect." (PMID 32823812, 2020). "While in chronic myeloid leukemia (CML) the CXCR4 is downregulated, thereby promoting the mobilization of progenitor cells into blood, the receptor is highly expressed in breast cancer cells, favoring the migratory capacity of these cells." (PMID 32075106, 2020). "Several proteins overexpressed in bone-seeking breast cancer cells were associated with increased migration and invasiveness in bone metastasis, including Osteoactvin, Cadherin-11, MMP-9 and CXCR4." (PMID 32226538, 2020). "Elevated expression of CXCR4 has been reported in human mammary cancer, melanoma and B cell non-Hodgkin’s lymphoma (NHL)." (PMID 33166332, 2020). "Recently, a cyclam-based small molecule radioprobe [18F]MCFB was developed and evaluated for imaging of CXCR4 expression in breast carcinoma xenografts." (PMID 31652624, 2019). "Nuclear CXCR4 expression has been observed in several malignant tumors, such as breast cancer, colorectal cancer, pancreatic adenocarcinoma, thyroid carcinoma, and prostate cancer." (PMID 30177838, 2019). "The chemokine receptor CXCR4 is expressed in BCSCs and is a key chemokine receptor involved in metastasis of breast cancer and forms a target in restraining or removal of BCSCs." (PMID 31681564, 2019). "CXCR4 is highly expressed in human breast cancer cells, while SDF-1α exhibits peak levels of expression in organs such as the lymph node, lung and brain." (PMID 31219799, 2019). "Another study reported this compound to be a novel inhibitor of CXCR4 and thus found to hold immense potential in suppressing metastasis in pancreatic cancer and also in case of breast cancer, the most predominant cancer type among women across the world." (PMID 31759370, 2019). "CXCR4 encodes a G protein-coupled receptor protein that binds to CXCL12 ligand and is highly expressed in patients with breast cancer." (PMID 30642351, 2019).
breast carcinoma (continued). "Invivo, neutralizing the interactions of CXCR4/SDF-1α significantly impairs breast cancer cell metastasis to regional lymph nodes." (PMID 31219799, 2019). "Zerumbone also inhibited invasion and metastasis in breast cancer by downregulating the expression of CXCR4." (PMID 30781671, 2019). "Both ARBs and CXCR4 inhibitors have been translated into clinical trials in cancer patients, and additional clinical trials are needed to accelerate the development of breast cancer treatment strategies." (PMID 31219799, 2019). "Studies have shown that treatment with DOX at 4 μg/mL increased CXCR4 expression, a chemokine involved in metastasis in breast cancer." (PMID 31614718, 2019). "CXCR4 has been identified to be one of the major chemokine receptors involved in breast cancer metastasis." (PMID 31106142, 2019). "In particular, miR-21, MMP1, MMP9, MMP13, CXCR4 and vimentin were found overexpressed in the invasive margins of breast cancer tissues of clinical samples and in the cancer cell lines; E-Cadherin, on the other hand, was decreased." (PMID 31362429, 2019). "VEGF, an efficient promoter of endothelial cell migration in angiogenesis, has been demonstrated to stimulate breast carcinoma invasion utilizing chemokine receptor C-X-C chemokine receptor type 4 (CXCR4) affinity toward stromal-derived factor 1 (SDF-1)." (PMID 29478325, 2019). "CXCL12 presentation was spatially controlled at the ventral side of breast cancer cells inducing lamellipodia and filopodia mediated by CXCR4." (PMID 31332163, 2019). "Several reports have found that CXCR4 was upregulated in a variety of cancers, including lung cancer, breast cancer colorectal cancer, and prostate cancer." (PMID 31073530, 2019). "CXCR4 overexpression in breast cancer has been shown to promote metastasis in an organ-specific manner, and new treatments targeting this pathway in TNBC have had some success." (PMID 30642351, 2019). "Evidence have shown that CXCR4 drives the metastatic phenotype in breast cancer through induction of CXCR2 and activation of MEK and PI3K pathways, while MMP3 contributes to the precision of epithelial cell branching via the processing of ECM components." (PMID 31798768, 2019). "In particular, the expression of miR-146a was shown to reduce proliferation and to induce apoptosis in breast cancer cells, as well as to suppress CXCR4-mediated breast cancer migration." (PMID 31878316, 2019). "TNBC expresses CXCR4 more frequently than other breast cancer subtypes, and high expression levels of CXCR4 are related to a high histological grade of TNBC and high incidences of recurrence and cancer-related death." (PMID 32047724, 2019). "Experiments with breast cancer cell lines showed that inhibition of the chemokine receptor CXCR4 by a neutralizing antibody abrogates their metastasis to the lung, which expresses the corresponding chemokine ligand, CXCL12." (PMID 31477571, 2019). "The involvement of CXCL12/CXCR4 axis is well known in metastatic spreading, drug resistance, and overall worse diagnosis in breast carcinoma." (PMID 31652624, 2019). "Transfection properties of siRNA/L1 polyplexes were studied in CXCR4-positive breast cancer cells MDA-MB-231 and endothelial cells EA.Hy926." (PMID 31174285, 2019). "For example, breast cancer was found to express the chemokine receptors CXCR4 and CCR7 at high levels." (PMID 31533220, 2019). "For instance, the split FLuc methodology was used in cell culture models as well as in tumor xenograft models of breast cancer (see Section 8) to measure changes in chemokine receptor CXCR4 (and CXCR7) homodimerization in response to pharmacological agents." (PMID 31213021, 2019). "Among all of these chemokines in breast cancer, CXCR4/SDF-1α is a major chemokine pair involved in lymph node metastasis." (PMID 31219799, 2019). "One study showed that oncolytic viruses expressing the CXCR4 antagonist inhibit breast cancer metastases in a mouse model." (PMID 31817646, 2019).
breast carcinoma (continued). "CXCL12 is a chemokine and via the CXCR4/CXCL12 axis of breast cancer cells induces a chemotactic response and invasion." (PMID 31341222, 2019). "Even though CXCR4 nuclear localization has been described in RCC, breast cancer, prostate cancer, and colon cancer, there are debates as to whether this localization is associated with poor prognosis, and the biological function of the subcellular localization of CXCR4 is unclear." (PMID 30177838, 2019). "NR2F1 provokes a reduction in chemokine CXCL12 expression and enhancement of CXCR4 expression, and it stimulates breast cancer cell migration." (PMID 31146704, 2019). "It was also shown that CXCR4 upregulated VEGF expression through the Akt signaling pathway in breast cancer." (PMID 31336612, 2019). "In this study, we suggest that CXCR4 can feed into this complex thereby having a significant impact on synthesis of oncogenic proteins needed for breast cancer survival and invasion." (PMID 31106142, 2019). "Upon binding with the chemokine CXCL12, the chemokine receptor CXCR4 has been shown to promote breast cancer progression." (PMID 30441765, 2018). "ERβ isoform is known to undergo phosphorylation in response to CXCR4 activation, resulting in activation in breast cancer cells." (PMID 30051594, 2018). "Unbinding force maps depicted regions of the breast cancer cell surfaces that have high unbinding forces, likely due to CXCR4 colocalization within lipid rafts." (PMID 29973594, 2018). "In mouse breast cancer models, inhibitors of CXCR4 significantly reduce the number of breast cancer metastatic cells to lymph nodes." (PMID 29783989, 2018). "Of clinical interest, CXCL12/CXCR4 levels are increased in many cancers, including breast cancer, pancreatic cancer, oral squamous cell carcinoma, ovarian cancer, cervical carcinoma, and gastric cancer." (PMID 30420856, 2018). "Consistently, antagonizing CXCR4 inhibited lung metastasis of human tongue squamous cell carcinoma, esophageal cancer, breast cancer in immunocompromized mice." (PMID 30622535, 2018). "In this study, we examined the potential effect of thymoquinone (TQ), derived from the seeds of Nigella sativa, on the expression and regulation of CXCR4 in breast cancer cells." (PMID 30564115, 2018). "For example, heregulin stimulation of ErbB3 and ErbB4 causes upregulation of C-X-C chemokine receptor type 4 (CXCR4) and increases Rac1 activation through a stromal cell-derived factor (SDF)-1-CXCR4 mediated PREX1 GEF mechanism in breast cancer cells." (PMID 30261690, 2018). "Radiation-induced modifications in SDF-1/CXCR4 signaling, in turn, have been reported in gliomas, mesotheliomas, prostate, cervical, lung and breast cancer." (PMID 30622535, 2018). "In conclusion, the results indicate that TQ primarily exerts its anti-metastatic effects by down-regulation of NF-κB regulated CXCR4 expression and thus has potential for the treatment of breast cancer." (PMID 30564115, 2018). "The aim of this retrospective analysis was to assess the diagnostic performance of CXCR4-directed PET imaging in patients with breast cancer using the recently introduced CXCR4-targeted PET probe 68Ga-Pentixafor." (PMID 30191351, 2018). "A variety of peptides and small molecules targeting CXCR4 attenuate the growth of breast cancer both in vivo and in vitro." (PMID 30513833, 2018). "Testosterone treatment induces both CXCL12 and CXCR4 expression in ER+ve breast cancer cells but only if AR and SRC1 are co-expressed." (PMID 30416486, 2018). "Recently, CXCR4 has been shown to drive the metastatic phenotype in breast cancer through the activation of MEK and PI3K pathways." (PMID 30486409, 2018). "Some studies have found that SDF1 and CXCR4 are highly expressed in cholangiocarcinoma, breast cancer, non-small cell lung cancer, cervical cancer, liver cancer Huh7 cells and melanoma cells." (PMID 29783989, 2018).
breast carcinoma (continued). "The overexpression of CXCR4 in breast cancer cells resulted in increased bone metastasis formation, whereas CXCR4 inhibition significantly reduced metastatic burden in an experimental model of prostate cancer bone metastasis." (PMID 29642534, 2018). "On the other hand, CXCR4 has been found to be a prognostic marker in a variety of cancers, including breast cancer." (PMID 30109213, 2018). "On the other hand, CXCR4 is mainly expressed in primary breast cancer lesions and lymph node metastases." (PMID 30012106, 2018). "In the attempt to blockade Nef, we discovered that our CXCR4 antagonists demonstrate profound apoptotic activity against MDA-MB-231 breast cancer cells in vitro similar to the effect of Nef M1 peptide." (PMID 29682200, 2018). "There is a strong correlation of PDZK1 with multiple signaling pathways including estrogen dependent IGF-1R and chemokine (C-X-C motif) receptor 4 (CXCR4) signaling which can be targeted therapeutically to treat breast cancer." (PMID 29787591, 2018). "The chemokine receptor CXCR4 plays an integral role in the development of highly metastatic breast cancer and in the pathogenesis of chronic HIV infection." (PMID 29682200, 2018). "To determine if CXCR4 antagonism prevents M1-induced apoptosis in other cell types, we chose to work with the breast cancer cell line MDA-MB-231 which over-expresses CXCR4." (PMID 29682200, 2018). "Using Affymetrix expression data from 29 lung and 22 breast carcinoma brain metastases, we again were unable to find a correlation between CXCR4 and EGFR expression." (PMID 29721166, 2018). "The activation of NRF1 was studied in the context of the upregulation of the CXCR4 gene involved in the development of E2-dependent breast cancer." (PMID 30486409, 2018). "In carcinomas of the breast and prostate, interactions of CXCR4 with RTKs have previously been reported." (PMID 29776413, 2018). "Collectively, these findings suggest our CXCR4 antagonists have promising clinical utility for HIV or breast cancer therapies as well as being useful probes to examine the link between CXCR4 and apoptosis." (PMID 29682200, 2018). "CXCR4 has been reported to be overexpressed in breast cancer, prostate cancer, glioma, cervical cancer, lung cancer, and colorectal carcinoma." (PMID 30104400, 2018). "Here, the authors present a method to block CXCR4 and thereby inhibit breast cancer metastasis by developing a liposome that presents CXCR4-binding peptides in a multivalent fashion." (PMID 29973594, 2018). "For example, the chemokine receptors CXCR4 and CCR7 have been found to be involved in breast cancer metastasis, and both CXCR4 and CCR5 have been successfully used as drug targets for haematopoietic stem cell mobilization and HIV inhibition." (PMID 30497370, 2018). "Prior to screening in both Jurkat and breast cancer cells, two assays were used to characterize their interaction with CXCR4: (i) CXCL12 induced calcium flux; and (ii) the HIV-1IIIB MAGI entry assay." (PMID 29682200, 2018). "The expression of CXCR4 is also upregulated in patients with late-recurring breast cancers, further supporting its involvement in dormancy." (PMID 29642534, 2018). "Immunohistochemical staining for CXCR4 of open surgery specimens was available in seven primary breast cancers." (PMID 30191351, 2018). "A recent publication of our group evaluated the feasibility of CXCR4-targeted PET in three patients with breast cancer amongst other solid cancers." (PMID 30191351, 2018). "Previous studies reported that breast cancer cells exhibit different ratios of membrane localized versus cytoplasmatic CXCR4." (PMID 30191351, 2018). "NT21MP reversed the EMT in breast cancer cells via PDGFRα and exerted anti-glioma effect by specifically combining with CXCR4." (PMID 30104400, 2018). "This was shown to have consequences for metastasis, as IGF1R/CXCR4-expressing breast cancer cells have a higher potential to metastasize to bone." (PMID 29774124, 2018).
breast carcinoma (continued). "The contribution of CXCR4 to reprogramming breast cancer cells to cancer stem cells is of particular interest to our research on NRF1." (PMID 30486409, 2018). "We previously reported that M1 exhibits profound anti-proliferative activity against MDA-MB-231 breast cancer cells and posited that CXCR4 antagonism would protect these cells from M1." (PMID 29682200, 2018). "We separately observed that both ACKR3 and CXCR4 are overexpressed in breast cancer tumours of two patients with invasive ductal or lobular carcinoma, an increase also observed elsewhere." (PMID 30441765, 2018). "There have been few attempts to correlate CXCR4 with different molecular subtypes in human breast cancer." (PMID 30012106, 2018). "Strikingly, in MDA-MB-231 breast cancer cells, the loss of mdig appeared to favor the open chromatin structure of the genome for metastatic genes CXCL12, CXCR4, MMP-1, and MMP-9, while enhancing the formation of closed chromatin for UPA." (PMID 30254753, 2018). "NF-κB signaling and NF-κB subunit p65 regulate CXCR4 expression in breast cancer cells and neuroblastoma, and acetylation of p65 at lysine 310 (K310) regulates its DNA-binding activity and target gene transcription." (PMID 30013077, 2018). "Herein, we report that a series of small molecule CXCR4 antagonists can selectively induce apoptosis in MDA-MB-231 breast cancer cells at sub-nanomolar concentrations." (PMID 29682200, 2018). "SDF-1 can specifically mediate the chemotactic movement, invasion and metastasis of breast cancer cells through CXCR4, and atypical chemokine receptor CXCR7." (PMID 29305742, 2018). "Silencing CXCR4 expression in breast cancer cell lines significantly decreased colony formation and overexpression of CXCR4 had the opposite effect." (PMID 29959873, 2018). "This role is exerted by H-ferritin via multiple mechanisms such as the regulation of CXCL12/CXCR-4 axis in breast cancer cells or the modulation of a specific microRNA pattern in ovarian cancer cells." (PMID 30518922, 2018). "Recent studies on breast cancer found that the expression profiles of CXCR4 are very diverse among the primary tumor of breast cancer, the metastatic tumor tissues, and the PDX tumors filtered by specific murine microenvironment." (PMID 29534550, 2018). "CXCR4 has been described to transactivate EGFR in breast cancer cells and in ovarian cancer cells in which it leads to both mitogen-activated protein kinase and AKT activation." (PMID 28423060, 2017). "CXCL12, also known as stromal cell–derived factor-1 (SDF-1α), binds to CXCR4, which is often overexpressed in breast cancer and has been correlated with poor clinical outcome." (PMID 28415580, 2017). "Tac1 expression in the breast cancer cell lines was found to play a key role in bone marrow EC transmigration and the adherence of the metastatic cells to MSCs through the regulation of CXCR4 and SDF-1α production in the breast cancer cells." (PMID 28148268, 2017). "RNA immunoprecipitation (RIP) demonstrated that BAG3 was recruited to CXCR4 mRNA in breast cancer cells." (PMID 28703799, 2017). "Real-time PCR confirmed that floating culture and BAG3 overexpression increased CXCR4 mRNA levels in breast cancer cells." (PMID 28703799, 2017). "Here, we aimed to investigate the delivery efficiency of siRNA by chitosan into breast cancer cells, and then to examine the regulatory role by chitosan nanoparticle-delivered siRNA on CXCR4 expression and on the chemosensitivity of breast cancer cells." (PMID 28446538, 2017). "Real-time RT-PCR demonstrated that BAG3 knockdown decreased total CXCR4 mRNA, while nascent CXCR4 mRNA was unaltered in breast cancer cells." (PMID 28703799, 2017). "Taken together, this is the first study to describe a novel role of BAG3 in post-transcriptional regulation of CXCR4 via interaction with its transcript in breast cancer, by which promotes BCSC-like properties." (PMID 28703799, 2017).